IFNG-AS1 (IFNG regulatory antisense RNA 1)
Synonyms: Tmevpg1; LincR-Ifng-3'AS; NEST; GS1-410F4.2
Gene: Long non-coding RNA gene on chromosome 12 (67,989,446 to 68,234,686, forward strand). Ensembl gene ENSG00000255733.
Diseases named in the same sentence as IFNG-AS1 in open-access papers:
IFNG-AS1 is named in the same sentence as 30 diseases in open-access papers, as found by Europe PMC text mining. Sharing a sentence is not in itself a finding about the gene and the disease. The quoted sentences say what the papers report.
autoimmune disease (3 papers, 2022 to 2025). A disorder resulting from loss of function or tissue destruction of an organ or multiple organs, arising from humoral or cellular immune responses of the individual to their own tissue constituents. "IFNGAS1 lncRNA has been associated with autoimmune diseases, including asthma." (PMID 36743692, 2023). "Aberrant expressions of IFNG-AS1 and GAS5 are directly linked to numerous autoimmune disorders but their levels in childhood ITP are still obscure." (PMID 36310591, 2022).
Salmonella Infections (3 papers, 2013 to 2024). Infections with bacteria of the genus SALMONELLA. "Hosts deficient in IFNG-AS1 exhibit increased vulnerability to fatal infection with Salmonella enteritidis, highlighting the crucial role of IFNG-AS1 in the host defense against Salmonella infections." (PMID 38542512, 2024).
Sjögren syndrome (3 papers, 2018 to 2023). "In Sjogren’s Syndrome, increased expression of TMEVPG1 lncRNA (IFNG-AS1—IFNG antisense RNA 1) was detected in CD4+ T lymphocytes and positively correlated with Th1 cell proportion among CD4+ T cells." (PMID 29751665, 2018).
viral infection (3 papers, 2013 to 2022). "The lncRNA transcript Tmevpg1, also called NeST or Ifng-AS1, was originally discovered in the context of Theiler’s virus infection, and the researchers found that mice without Tmevpg1 expression could not control intracranial viral infection." (PMID 35794862, 2022).
asthma (2 papers, 2016 to 2023). "We selected the most upregulated differentially expressed lncRNA CRNDE and IFNGAS1 in asthma for our follow-up experiments." (PMID 36743692, 2023). "This study also suggests a potential role for new loci, namely, SYNE1, LINGO2, and IFNG-AS1, in the pathogenesis of asthma." (PMID 27445529, 2016).
cutaneous leishmaniasis (2 papers, 2025). Leishmaniasis affecting the skin. "Statistical comparison of genotypic and allelic frequencies of the rs7134599 variant of IFNG-AS1 between patients with Leishmania guyanensis-cutaneous leishmaniasis and healthy controls from the same endemic areas." (PMID 40658679, 2025). "We investigated the association of two genetic variants of IFNGAS-1, rs4913269 and rs7134599, with susceptibility or protection to Leishmania guyanensis- induced cutaneous leishmaniasis (Lg-CL)." (PMID 40658679, 2025).
rheumatoid arthritis (2 papers, 2020 to 2025). A chronic, systemic autoimmune disorder characterized by inflammation in the synovial membranes and articular surfaces. "However, the effect of its human ortholog, IFNG-AS1, on the pathogenesis of rheumatoid arthritis (RA) remains unclear." (PMID 32377535, 2020).
acute leukemia (1 paper, 2021). A clonal (malignant) hematopoietic disorder with an acute onset, affecting the bone marrow and the peripheral blood. "lncRNA interferon (IFN) gamma antisense RNA 1 (IFNG-AS1) also called TMEVPG1 or NeST, was first reported in the immune system of diseases and acted crucial oncogenic role in several types of cancers, such as pituitary adenomas, breast cancer, and acute leukemia." (PMID 34872454, 2021).
colon adenocarcinoma (1 paper, 2021). "The silence of IFNG-AS1 repressed the tumor proliferation, invasion, and migration in colon adenocarcinoma cells in vitro by sponge to miR-627-3p." (PMID 34872454, 2021). "The expression of IFNG-AS1 was firstly tested in the tumor tissues of colon adenocarcinoma patients and it could be seen that IFNG-AS1 expression was also climbed in tumor tissues rather than normal tissues." (PMID 34872454, 2021). "Beyond that, downregulated expression of IFNG-AS1 may repress malignant progression of colon adenocarcinoma by regulating miR-627-3p." (PMID 34872454, 2021).
colon adenoma (1 paper, 2021). An adenoma that arises from the colon. "The increased IFNG-AS1 expression was observed in both colon adenoma and adenocarcinoma patients compared to control samples." (PMID 34872454, 2021). "Nevertheless, whether IFNG-AS1 was abnormally expressed in colon adenoma and adenocarcinoma remains unknown." (PMID 34872454, 2021).
COVID-19 (1 paper, 2025). A disease caused by infection with severe acute respiratory syndrome coronavirus 2. "Our results suggest that IFNG-AS1 variants may also contribute to response to corticoid treatments in COVID-19 patients." (PMID 40149530, 2025).
lung carcinoma (1 paper, 2025). "Furthermore, AI has shown that new biomarkers, such as CCDC26 and interferon gamma antisense RNA 1 (IFNG-AS1), may be related to lung cancer and Small Nucleolar RNA Host Gene 3 (SNHG3) may be associated with PD-L1." (PMID 40075729, 2025).
infection (6 papers, 2014 to 2024). The state of being infected such as from the introduction of a foreign agent such as serum, vaccine, antigenic substance or organism. "Although one model is generally indicated that Ifng-AS1(NeST) was required for Ifng expression in response to infection with Salmonella, and Ifng-AS1(NeST) was found to bind WDR5 component of histone H3 lysine 4 methytransferase complex, and to modify H3K4me3 at the Ifng locus by CD8+ T cells." (PMID 26634912, 2015).
tumor (4 papers, 2021 to 2025). "Whereas the HMGA2::MSRB3 and HMGA2::FHIT fusions were described in previous studies, the remaining detected fusion partners such as ARID2 or IFNG-AS1 are novel in this tumor type." (PMID 40033554, 2025).
cancer (3 papers, 2016 to 2023). A tumor composed of atypical neoplastic, often pleomorphic cells that invade other tissues. "Among the 26 upregulated genes, IFNG-AS1, AC093818.1, AF127936.5, and OLMALINC were expressed in different diseases, especially IFNG-AS1, which has been reported in many malignant tumors." (PMID 37342185, 2023).
IFNG-AS1 also shares sentences with these, for which no sentence is quoted: adenocarcinoma (1 paper); autoimmune disorders (1); bacterial infections (1); breast carcinoma (1); Hashimoto thyroiditis (1); hepatocellular carcinoma (1); immune system disorder (1); inflammatory bowel disease (1); leishmaniasis (1); lupus nephritis (1); ocular toxoplasmosis (1); pituitary adenomas (1); protozoal infections (1); schizophrenia (1); ulcerative colitis (1).